RTCA (RNA 3'-terminal phosphate cyclase)
Description:
Catalyzes the conversion of 3'-phosphate to a 2',3'-cyclic phosphodiester at the end of RNA. The mechanism of action of the enzyme occurs in 3 steps: (A) adenylation of the enzyme by ATP; (B) transfer of adenylate to an RNA-N3'P to produce RNA-N3'PP5'A; (C) and attack of the adjacent 2'-hydroxyl on the 3'-phosphorus in the diester linkage to produce the cyclic end product. Likely functions in some aspects of cellular RNA processing. Function plays an important role in regulating axon regeneration by inhibiting central nervous system (CNS) axon regeneration following optic nerve injury.
Synonyms: RPC; RTC1; RTCD1
Tractability: PROTAC: ubiquitination databases record sites on it; its protein half-life has been measured.
Gene: Protein-coding gene on chromosome 1 (100,266,160 to 100,292,769, forward strand). Ensembl gene ENSG00000137996.
Subcellular location: Nucleus, nucleoplasm
Subcellular location (Human Protein Atlas): Nucleoplasm
Gene Ontology:
Molecular function: RNA binding; RNA-3'-phosphate cyclase activity; catalytic activity
Biological process: negative regulation of optical nerve axon regeneration; RNA processing
Cellular component: nucleoplasm; nucleus
Genetic constraint (gnomAD): Loss-of-function variants: 29 observed, 33.24 expected, observed/expected ratio (o/e) 0.87, 90% interval 0.65 to 1.19. The upper end of that interval is the gene's LOEUF score, 1.19, which puts it in group 5 of 6, group 1 being the genes least tolerant of losing a copy. Missense variants: 319 observed, 341.84 expected, observed/expected ratio (o/e) 0.93, 90% interval 0.85 to 1.02. Synonymous variants: 129 observed, 123.51 expected, observed/expected ratio (o/e) 1.04, 90% interval 0.9 to 1.21.
Homologues: Orthologues: chimpanzee RTCA (99% identical), macaque RTCA (98% identical), dog RTCA (95% identical), rabbit RTCA (95% identical), pig RTCA (95% identical), rat Rtca (91% identical), mouse Rtca (90% identical), tropical clawed frog rtca (74% identical), zebrafish rtca (74% identical), Drosophila melanogaster Rtca (39% identical). Paralogues in human: RCL1 (27% identical).
Diseases named in the same sentence as RTCA in open-access papers:
RTCA is named in the same sentence as 6 diseases in open-access papers, as found by Europe PMC text mining. Sharing a sentence is not in itself a finding about the gene and the disease. The quoted sentences say what the papers report.
myasthenia gravis (1 paper, 2019). Myasthenia gravis (MG) is a rare, clinically heterogeneous, autoimmune disorder of the neuromuscular junction characterized by fatigable weakness of voluntary muscles. "By comparing transcriptome of thymoma with and without myasthenia gravis, we found that 5 genes (PNISR, CCL25, NBPF14, PIK3IP1 and RTCA) were upregulated more than 2-fold, and that more than 30 genes were downregulated more than 2-fold." (PMID 30787364, 2019).
tumor (1 paper, 2024). "Furthermore, the A3A-most and A3B-most tumors separately cluster together suggesting that these two independent ways of defining relative contribution of A3A and A3B to tumor mutations (i.e., HS1/HS2 and RTCA/YTCA ratios) are roughly equivalent." (PMID 38499553, 2024).
RTCA also shares sentences with these, for which no sentence is quoted: cancer (1 paper); oral squamous cell carcinoma (1); psychotic disorder (1); thymoma (1).